ABCC11 (ATP binding cassette subfamily C member 11)
Diseases named in the same sentence as ABCC11 in open-access papers (continued):
Sharing a sentence is not in itself a finding about the gene and the disease.
pancreatic cancer (1 paper, 2021). "The ABCC11 gene, which was highly expressed in liver samples in addition to ABCC5, was expressed at a very low level in pancreatic tumour." (PMID 34132895, 2021). "Thus, it is not likely that FdUMP efflux through ABCC11 contributes to 5-FU drug resistance as much as ABCC5 in pancreatic cancer." (PMID 34132895, 2021).
prostate carcinoma (1 paper, 2024). A carcinoma that arises from epithelial cells of the prostate gland. "ABCC11 has not previously been found to have an association with prostate cancer and was also not a BCR-free survival related DEG, nor was in associated with the clinical variable in post-hoc analysis." (PMID 39352906, 2024).
sarcoidosis (1 paper, 2024). Sarcoidosis is a multisystemic disorder of unknown cause characterized by the formation of immune granulomas in involved organs. "ABCC11 is a gene that influences macrophage differentiation and induces TNF-α and IL17 through TLR4 signaling; these results as well as the novel findings above support the importance of innate immune response genes in sarcoidosis." (PMID 39080656, 2024). "Our integrated model also demonstrated differential expression/methylation of IL20RB, ABCC11, SFSWAP, AGBL4, miR-146a-3p, and miR-378b between non-progressive and progressive sarcoidosis." (PMID 39080656, 2024).
triple-negative breast carcinoma (1 paper, 2016). An invasive breast carcinoma which is negative for expression of estrogen receptor (ER), progesterone receptor (PR), and human epidermal growth factor receptor 2 (HER2). "However, the degree to which ABCC11 contributed to eribulin resistance was much higher in MCF7 cells, which are positive for ERα, than in the triple-negative breast cancer cell lines." (PMID 27588398, 2016).
tumor (16 papers, 2008 to 2025). "Differentially expressed genes (DEGs) between domain 4 and domain 13 includes ABCC11, ABCC12 and TFF1, in which the first two are multidrug resistance genes and the last one is associated with tumour differentiation." (PMID 36250636, 2022). "Immunohistochemistry gradings for 5 biomarkers (CD44, ABCC4, ABCC11, N-Cadherin and pan-Cadherins) and 3 clinical parameters (tumor size, tumor grade and node status) of 298 patient cohort were used to develop a machine learning based statistical algorithm." (PMID 30894144, 2019). "It uses a machine learning algorithm to compute a risk score for distant recurrence over a timeline of five years with the inputs from IHC gradings of five biomarkers (CD44, ABCC4, ABCC11, N-Cadherin, and pan-Cadherin) along with three clinical parameters (node status, tumor size, and tumor grade)." (PMID 39944436, 2025). "We highlight a small population of cells, a subcluster located in between tumor and myoepithelial populations which coexpress tumor (ERBB2, ABCC11) and myoepithelial markers (MYLK, DST) (a′)." (PMID 38114474, 2023). "Over-expression of ABCC11 in sphere-forming cells suggests that the CSC population in NPC is resistant to chemotherapeutic drugs and thus contribute to tumor recurrence." (PMID 23285037, 2012). "ABCC11 and ABCC12 were highly expressed in miR-18a/low tumours of the METABRIC dataset." (PMID 38786043, 2024).
cancer (13 papers, 2010 to 2025). A tumor composed of atypical neoplastic, often pleomorphic cells that invade other tissues. "Taken together, EXOC6/rs1339820 and ABCC11/rs75797074 showed some cross-cancer susceptibility in CG and CRC, and LRP5L maybe a potential susceptibility gene in GI cancers." (PMID 37483484, 2023). "ABCC11/rs75797074, a significant SNP associated with risk of all three cancers (yet not passed the ASSET testing threshold), was successfully validated in the CRC and ESCC datasets." (PMID 37483484, 2023). "Thus, our findings, together with the results of previous studies, demonstrate that ABCC11 is involved in the alteration of fluorouracil sensitivity in cancer cells." (PMID 27588398, 2016). "Since histone deacetylase inhibitors can be utilized in combination with conventional anti-cancer drugs in clinical trials, such induction of the ABCC11 WT may affect the efficacy of nucleoside-based chemotherapy." (PMID 23316210, 2012). "Since histone deacetylase inhibitors can be utilized in combination with conventional anti-cancer drugs in clinical trials, such induction of ABCC11 WT may affect the efficacy of nucleoside-based chemotherapy." (PMID 21182469, 2010). "Thus, it is clear that ABCC11 is involved in altering eribulin sensitivity in cancer cells." (PMID 27588398, 2016). "Although in our EVs from eribulin-treated cancer cells, ABCC11 mRNA was not up-regulated, we found that both ABCC2 (log2FC = +4.570, about 23 times more) and ABCG2 (log2FC = +2.366, about 5 times more) were up-regulated." (PMID 38534323, 2024). "In addition, MDCKII cells stably expressing ABCC11-EGFP were more resistant to 5-FU, an anti-cancer drug, than mock MDCKII cells which were constructed with a pEGFP-N1 vector." (PMID 27281343, 2016). "Six of these genes were not expressed or were very weakly expressed (ABCC11, SLC22A6, SLC22A7, SLC22A8, SLC22A9, SLCO1B1), and among the other eight genes, only gene ABCG2 showed significant difference in expression in cancer versus adjacent control tissue." (PMID 33917029, 2021).
adenocarcinoma (3 papers, 2010 to 2019). A common cancer characterized by the presence of malignant glandular cells. "They further analyzed the relationship between the ABCC11 gene expression and MTA sensitivity of 13 adenocarcinoma cell lines." (PMID 23316210, 2012). "They further analyzed the relationship between ABCC11 gene expression and MTA sensitivity of 13 adenocarcinoma cell lines." (PMID 21182469, 2010).
metabolic disorders (1 paper, 2021). "However, total BAs, and Abcc3, Abcc11, Cyp7a1 mRNA levels were unchanged in this study, suggesting that there might be a dynamic equilibrium of total BAs in GUDCA-alleviated diet-induced metabolic disorders." (PMID 34236076, 2021).
ABCC11 also shares sentences with these, for which no sentence is quoted: acute myeloid leukemia (3 papers); Acute otitis media (1); diabetes (1); episodic kinesigenic dyskinesia 1 (1); familial cold autoinflammatory syndrome 1 (1); hepatocellular carcinoma (1); Hyperhidrosis (1); mucositis (1); Obesity (1); otitis media (1); retinitis pigmentosa (1); skin melanomas (1); Wilms tumor (1).